CD4 (CD4 molecule)
Diseases named in the same sentence as CD4 in open-access papers (continued):
Sharing a sentence is not in itself a finding about the gene and the disease.
ovarian carcinoma (continued). "The detection of conventional and Tbet+ Treg populations in OPSCC and CxCa confirmed studies reporting the presence of CD4+Foxp3+ T cells co-expressing Tbet in chronic hepatitis C driven liver cancer, oral squamous cell carcinoma and ovarian cancer." (PMID 30658697, 2019). "There is still debate in the literature concerning the role of the Th17 CD4+ T cell subset in ovarian cancer, but some have reported that these cells have an inverse relationship with Tregs, and correlate with survival." (PMID 30200478, 2018). "In ovarian cancer, pDC induced IL-10 secreting CD4+ and CD8+ Tregs and enhanced angiogenesis, mediated by the secretion of TNF-α and IL-8." (PMID 30200478, 2018). "For example, coculture CD8+ cells with ovarian cancer cell line can induce CD8+ Tregs that can inhibit naïve CD4+ T cell proliferation." (PMID 30643519, 2018). "To further examine any alteration in the distribution of cellular populations in immune cell compartment of ovarian cancer patient ascites, we analyzed the proportion of CD4+ (T helper cells) and CD8+ T-cells (T cytotoxic cells)." (PMID 30324091, 2018). "In line with the mouse data demonstrating the transdifferentiation of Th17 cells into IL-17negFoxp3+ cells, Foxp3 expression is induced in human IL-17A-producing ovarian cancer TALs when CD4+IL-17+ cells are restimulated under Treg-driving conditions." (PMID 28290453, 2017). "Compared with the Foxp3+ CD4+ T cells in ovarian cancer ascites of wild-type mice, the percentage of Helios+ subset of Foxp3+ cells infiltrating cancer ascites of RORγt−/− mice is significantly reduced." (PMID 28290453, 2017). "IL10 suppresses proinflammatory cytokine secretion, antigen presentation and CD4+ T cell activation and CCL22 is associated with regulatory T-cell migration in ovarian cancer." (PMID 28266500, 2017). "CD4+ T cells infiltrating the ovarian cancer ascites demonstrate a propensity towards either Foxp3-expressing or IL-17A-producing phenotype, implying that the developmental pathways of Treg and Th17 cells are mutually exclusive." (PMID 28290453, 2017). "Herein, we show for the first time that a higher fraction of TNFR2+ expressing T cell subsets, particularly on CD4+CD25hiFoxP3+ (Tregs) can also be induced de novo from healthy donor PBMCs conditioned with cell-free ovarian cancer ascites." (PMID 29163543, 2017). "Apart from Helios, the percentage of PD1+ Foxp3+ CD4+ cells in ovarian cancer of RORγt−/− mice (42.4±2.97% (control) and 24.55±4.89 (RORγt−/−), n=5 per group) is significantly lower." (PMID 28290453, 2017). "Both TGF-β and ovarian cancer conditioned medium upregulate Foxp3 expression in human CD4+IL-17A+ TALs compared with control and Th17-driving conditions." (PMID 28290453, 2017). "In the ascites of ovarian cancer patients, the frequencies of IL-10+ B cells are also positively correlated with the frequencies of CD4+Foxp3+ Tregs." (PMID 27331871, 2016). "In high-grade epithelial ovarian cancers (EOCs) patients, CD20+ infiltrates are strongly associated with all three T-cell subsets (CD3, CD4, and CD8), as well as T-cell differentiation markers TIA-1, Granzyme B, and FoxP3." (PMID 27331871, 2016). "The quantitation of CD3 T cells and CD4 T cells in the stromal and intraepithelial compartments also reflects what has been observed in human ovarian cancer." (PMID 25992288, 2015). "Of immune suppressive mechanisms, CD4+ regulatory T cells (Tregs) are a primary means of immune evasion in ovarian cancers; these are CD4+ T lineage cells whose primary function is immune regulation." (PMID 23382860, 2013). "In the present study, we characterized Tim-3+ CD4 T cells in 100 specimens from human hepatocellular, cervical, colorectal and ovarian carcinoma patients." (PMID 23526963, 2013). "Curiel and colleagues reported that the presence of high numbers of CD4+FoxP3+ T cells in malignant ascites of patients with ovarian carcinomas correlated with advanced tumor staging and reduced survival." (PMID 23533029, 2013).
ovarian carcinoma (continued). "In an ovarian cancer model, TNFα-mediated induction of IL-17-producing CD4+ cells led to the recruitment of myeloid cells into the tumor microenvironment and resulted in enhanced tumor growth." (PMID 24454480, 2013). "In collaboration with others, we first suggested a role of tumor-infiltrating Tregs in ovarian cancer pathogenesis, reporting higher levels of CD4+ Tregs, measured with immunofluorescence, among cases with poorer survival." (PMID 23382860, 2013). "Herein, we assess the frequency and ratio of CD8+ central memory and effector T cells as well as CD4+ effector and regulatory T cells (Tregs) during the first 18 weeks of standard chemotherapy for ovarian cancer patients." (PMID 24213326, 2012). "In a murine HPV16-induced epithelial cancer and more recently in a model of transplanted ovarian cancer, CD4+ T cells have been shown to promote the recruitment of myeloid cells into tumors." (PMID 21633700, 2011). "Spontaneous CD4+ T-cell responses to the tumor-specific antigen NY-ESO-1 (ESO) are frequently found in patients with epithelial ovarian cancer (EOC)." (PMID 21829534, 2011). "Collectively, these data indicate that CD4+ T cells contribute positively to the induction of antitumor responses achieved through adoptive T cell transfer regimens in ovarian cancer, and likely in other tumors." (PMID 21076522, 2010). "T cells from patients with late-stage ovarian cancer contained increased proportions of regulatory CD25+CD4+ T cells, that secreted the immunosuppressive cytokine TGF-β." (PMID 16164749, 2005). "Specifically, CD4+ T, CD8+ T, and B cells have been linked to enhanced clinical outcomes, whereas regulatory cell types, such as regulatory T cells and neutrophils, have been associated with poorer outcomes in ovarian cancers." (PMID 40953111, 2025). "The percentage of CD3+CD4+PD-1+ or CD3+CD8+PD-1+ T cell population in PBMCs could predict the outcome of ovarian cancer in this study." (PMID 41011166, 2025). "Tregs in ovarian cancer commonly express high levels of CD4, CD25, and FOXP3." (PMID 40703514, 2025). "Currently, immune cells and stromal cells such as Th cells and fibroblasts in breast cancer, fibroblasts in melanoma, CD8+ T cells, DCs in lung cancer, and macrophages, CD4+ T cells, and DCs in ovarian cancer have all been reported as potential LTo cells that secrete homeostatic chemokines." (PMID 39569184, 2024). "Patients with CCDC80-positive ovarian cancer have higher CD4 + memory-resting cells infiltration." (PMID 38872096, 2024). "Exosomes isolated by size exclusion chromatography and ultracentrifugation from the plasma of ovarian cancer patients potentially mediate the conversion of CD4+CD25neg T cells into CD4+CD25high FOXP3+ Tregs, which inhibits the function of CD8+ T cells and CD4+CD25neg T cells." (PMID 38796525, 2024). "However, several studies have demonstrated that IL-17 can suppress the progression of ovarian cancer by recruiting CD4+T and CD8+T cells to exert an anti-tumor effect." (PMID 39906741, 2024). "Intending to define the exact cellular composition of ACTBL2-expressing leukocytes in ovarian cancer, various common markers for the most frequent immune cell subtypes have been investigated—CD4 (T-helper cells), FOXP3 (regulatory T-cells) and CD56 for natural killer cells." (PMID 38114558, 2023). "In our RROS, we found that tumor-infiltrating lymphocyte counts are associated with peculiar gene expression patterns and bear prognostic information in ovarian cancer: CD4+ and CD45+ immune cell infiltration showed significant predictive power for overall survival." (PMID 37761986, 2023). "To provide more evidence for this hypothesis, we compared our findings to a recently published study of metabolomic profiles of purified CD45− tumour cells and CD45+ (CD8+ and CD4+) T cells from ovarian cancer tumours." (PMID 37337120, 2023).
ovarian carcinoma (continued). "The expression level of CCR8 in infiltrating CD4+ T cells of ovarian cancer tissue was significantly higher than that in peripheral blood of healthy controls and ovarian cancer patients, and high expression of CCR8 was significantly correlated with advanced tumor stage and poor differentiation." (PMID 37950246, 2023). "However, determining the expression levels of TILs in the ovarian cancer tissues found that 81% (n = 97) of ovarian cancer samples have TILs that express both of CD8 and CD4 and significantly associated with high PD-L1 expressions." (PMID 36604635, 2023). "Therefore, we believe that the high expression of CCL1 and CCL18 in ovarian cancer TME is an important factor in the increase of CD4+CCR8+ Tregs infiltration into tumor tissues." (PMID 37950246, 2023). "In addition, we found that PD-1 expression levels on CD4 T cells in the peripheral blood of ovarian cancer patients and healthy donors inversely correlate with serum methionine levels." (PMID 37147330, 2023). "Ascites-derived T cells from ovarian cancer patients have been reported to frequently express co-inhibitory receptors, which can lead to T cell dysfunction in ovarian cancer, and CD4+ T cells expressing the transcription factor FoxP3 usually favor tumor progression." (PMID 36607962, 2023). "In ovarian cancer, γδ T cells and their Vδ1 subset produced IL-17A, impaired antitumor responses, and enhanced immunosuppressive activities, as documented by their ability to inhibit the proliferation of naive CD4+ T cells upon co-culture with ovarian cancer tissue supernatants." (PMID 36793708, 2023). "Recent findings demonstrate that Cyst(e)inase treatment in combination with anti-PD-L1 checkpoint blockade synergistically enhanced T cell-mediated anti-tumor immunity, elevating tumoral lipid ROS and increasing populations of IFNγ/TNF expressing CD8 + /CD4 + T cells in an ovarian cancer model." (PMID 37170264, 2023). "The analysis of the immune microenvironment in this study showed that the expression level of CMTM1/2/3/6 had a certain correlation with the infiltration of a variety of immune cells (B cells, macrophages, neutrophils, dendritic cells, and CD4+ cells) in ovarian cancer." (PMID 36110202, 2022). "However, the CD4+ T cell–depleted mice showed a partial response that suggests a secondary role of CD4+ T cells in the overall antitumor response to RPE-mIL2 in ovarian cancer mice." (PMID 35235346, 2022). "Moreover, HODHBt enhanced the ability of IL-15-activated NK cells to kill HIV-infected CD4 T cells and different tumor cell lines, including chronic myelogenous leukemia, ovarian carcinoma, and glioblastoma cell lines." (PMID 35867565, 2022). "Interestingly, CD4 Th1 T cell responses from PBMCs from ovarian cancer patients and healthy donors were observed against citrullinated vimentin and enolase peptides." (PMID 36077528, 2022). "DEX can effectively inhibit the activation of IGF2 signal pathway, improve the immune function of ovarian cancer rats, inhibit the invasion and migration of ovarian cancer cells, and significantly increase the percentage of CD4+, CD8+ and the ratio of CD4+/CD8+." (PMID 35586059, 2022). "CD4/CD8 ratio was higher in ovarian cancer patients than benign tumor (malignant Vs." (PMID 35410290, 2022). "Other reports showed CD4+ TILs also have prognostic value in ovarian cancer." (PMID 34631788, 2021). "In the ovarian cancer microenvironment, IRE1α could suppress the mitochondrial activity in CD4 T cells and increase T cell infiltration." (PMID 34187252, 2021). "Similarly, Chen and collaborators showed after γδ TIL isolation that the Vδ1+ subset, the main population in ovarian cancer, displays reduced cytotoxic activity and inhibits the proliferation of CD4+ T-cells." (PMID 32599843, 2020).
ovarian carcinoma (continued). "Indeed, a recent report has demonstrated that EVs from ovarian cancers transit over long distances to the draining lymph node where they deliver arginase-1 to DCs resulting in a suppression of CD4+ and CD8+ T cell proliferation." (PMID 31921140, 2019). "In addition, ovarian cancer-associated pDCs have been characterized as expressing less IFN-α and stimulating higher levels of IL-10-expressing CD4+ T cells compared to their circulating counterparts." (PMID 31921140, 2019). "Our results provided independent edvidence that antigen presentation pathway is associated with ovarian cancer prognosis, and lends additional support for the crucial role of this machinery in TIL infiltration and defining CD8+/CD4+ T-cell responses against neoantigens." (PMID 31221207, 2019). "On the one hand, CD4+ T cells accumulating in tumors often belong to the Foxp3 expressing regulatory T cell subset, which can be induced by TAMs through IL-10 release as demonstrated in tumor tissues of ovarian cancer patients." (PMID 30853959, 2019). "CD8+ cytotoxic T cells kill tumor cells when they recognize an antigen that is presented by MHC class I. In ovarian cancer, tumor-infiltrating CD3+ and, more precisely, CD8+ T cells are associated with improved overall survival in advanced stage HGSC, as are high CD8/CD4 ratios." (PMID 30687337, 2018). "PD-L1 was upregulated in ovarian cancers, and anti-PD-L1 therapy could increase the proportion of CD4+ and CD8+ T cell (about 20%) and reduce regulatory T cell (about 5%) in mouse ovarian cancer model to promote tumor rejection." (PMID 32793247, 2018). "We also determined whether the Mo-DCs and tumor microenvironment, reflected by peritoneal fluid (PF) from type I or II ovarian cancer, could promote regulatory T cell (Tregs) differentiation from naive CD4+ lymphocytes in vitro." (PMID 28589429, 2017). "Our next objective was to determine whether Mo-DCs and PF from type I or II ovarian cancer can promote differentiation of Tregs from naive CD4+ lymphocytes in vitro." (PMID 28589429, 2017). "CD4+ T-reg cells rapidly decrease after primary tumor debulking in patients with ovarian cancer." (PMID 25331657, 2014). "Subsequent work supports the importance of CD4+ Tregs in ovarian cancer pathogenesis and outcome." (PMID 23382860, 2013). "Compared with peripheral blood and nontumor-infiltrating lymphocytes, the lymphocytes isolated from the corresponding tumor tissues of hepatocellular, cervical, colorectal and ovarian carcinoma patients contained significantly greater proportion of Tim-3+ CD4 T cells." (PMID 23526963, 2013). "Combined with two previous studies, which showed that gastric or ovarian cancer cells could induce the conversion of CD4+CD25− T cells into CD4+FoxP3+ Treg in vitro, we thought that most cancer cells might have the ability of the induction of Treg." (PMID 22174855, 2011). "In ovarian cancer tumor infiltrating CD4+ and CD8+ T cells have been studied extensively." (PMID 16164749, 2005). "Consistently, our study experimentally validated that Tregs inhibit CD8+ T-cell activity in ovarian cancer, and the observed differentiation trajectories suggest that the balance between proliferative and regulatory CD4+ T-cell states may modulate CD8+ T-cell function." (PMID 41008548, 2025). "However, γδ T cells sorted from OC tissues showed weakened cytotoxic activity against ovarian cancer cells, and γδ T cells cocultured with OC tissue supernatants could effectively inhibit the proliferative activity of naïve CD4+ T cells." (PMID 31064389, 2019). "Given that artesunate positively or negatively regulated miRNAs expression, we proposed the hypothesis that artesunate may down-regulate Sirt1 through miR-142 to promote Th1 differentiation from CD4+ T cells, thus enhancing its anticancer effect against ovarian cancer." (PMID 31038546, 2019).
ovarian carcinoma (continued). "Thus, immunotherapy strategies that modify the ratio of CD4+CD25+FOXP3+ Tregs or CD4+CD25+FOXP3- T cells to CD8+ effector cells may be useful in improving outcomes in ovarian cancer." (PMID 24244610, 2013). "This uniformity among such variable ovarian cancer patients, including serous, endometrioid, as well as mucinous carcinoma, some of which were metastatic, strongly suggests the presence of a common homeostatic mechanism that governs the regulation of CD4+ and CD8+ T cell subset levels in patients." (PMID 24213326, 2012). "The cytotoxic function of CD8+ T cells and the helper immune effects of CD4+CD25− T cells are central to the body’s anti-tumor immunity, and their functional impairment is a key feature of immune escape in ovarian cancer." (PMID 41394858, 2025). "Ovarian cancer cells utilize extracellular vesicles to deliver arginase ARG1 to immune cells, which inhibits the proliferation of CD4+ and CD8+ T cells by affecting their arginine metabolism, thereby suppressing antitumor immune responses." (PMID 41184266, 2025). "This study aims to elucidate the regulatory effects of VISTA+ Tfr cells on the functions of CD8+ T cells, CD4+CD25− T cells, and B cells, and to reveal their significance in the immune escape of ovarian cancer." (PMID 41394858, 2025). "The advantage of designing predictive models with ROMA and the frequency of PD-1+Tim-3+ expression in CD4+ T cells is that ROMA has high relevance and is widely used in the detection of ovarian cancer." (PMID 40870871, 2025). "First, regarding surface markers, senescent T cells are typically characterized as CD28-CD57+CD4+/CD8+ T cells 170-172, which is observed in many types of cancer, including lung cancer, ovarian cancer, head and neck cancer, and glioblastoma 173-176." (PMID 40860134, 2025). "In the early phase of TLS development in ovarian cancer, CXCL13-producing CD4 T cells were predominantly coincident with CD4 and CD8 T cells, and it transmigrated away from T cell zones to the CD21+ FDCs as TLS matured in ovarian cancer." (PMID 39076974, 2024). "IL-17 expression also correlates with a greater number of cytotoxic IFN-γ+CD4+ and IFN-γ+CD8+ T cells in ovarian cancer." (PMID 39906741, 2024). "VISTA, CTLA4, PDL1, PD1, CD8, CD4, and FOXP3 mRNA extracted from 429 patients with ovarian cancer in the Cancer Genome Atlas (TCGA) database was included as a validation cohort." (PMID 38634058, 2024). "In ovarian cancer, both CD8+ T cells and CD4+ T cells were observed to be the origin of CXCL13 and play important roles in mediating B-cell recruitment and TLS formation in human tumors." (PMID 39569184, 2024). "In a mouse model of ovarian cancer, TNF-α was found to stimulate the secretion of other cytokines, such as IL-17, by CD4+ T cells and indirectly promote tumor growth." (PMID 38644421, 2024). "Compared with high-grade epithelial ovarian cancer, low-grade cancer has higher intraepithelial CD8+ and CD4+ T-cell infiltration and CD8+/CD4+ ratio." (PMID 38303018, 2024). "The clinical samples also confirmed that the levels of immune microenvironment markers (CD1α and CD4) and ferroptosis markers (CHMP5 and DDIT3) were lower in high-grade ovarian cancer tissues." (PMID 38178187, 2024). "Mounting studies have indicated that several immune infiltrating cells are conducive to the favorable prognosis of patients with ovarian cancer, especially CD8+T cells, CD4+T cells, and natural killer cells." (PMID 38082211, 2024). "In conclusion, our study found that the increased IL‐6 and TNF‐α levels in recurrent ovarian cancer patients, while the decreased IFN‐γ level, the CD4+ T‐cell proportion, and the CD4+/CD8+ ratio." (PMID 37904699, 2023). "The mRNA expression of NFE2 members was significantly correlated with the immune infiltration of CD4+ T cells, CD8+ T cells, B cells, macrophages and neutrophils in Ovarian Cancer." (PMID 36650426, 2023).